FAP (fibroblast activation protein alpha)
Diseases named in the same sentence as FAP in open-access papers (continued):
Sharing a sentence is not in itself a finding about the gene and the disease.
rheumatoid arthritis (26 papers, 2006 to 2026). A chronic, systemic autoimmune disorder characterized by inflammation in the synovial membranes and articular surfaces. "Lastly, FAP and APCE are found in rheumatoid arthritis and osteoarthritis, where they are associated with joint inflammation, cartilage degradation, and disease severity." (PMID 39765634, 2024). "FAP is also found to be transiently expressed in healing wounds and in many non-oncological diseases in which activated fibroblasts are present, such as rheumatoid arthritis and different types of fibrosis." (PMID 40542914, 2025). "In 2015 Laverman and coworkers exploited the upregulation of FAP on activated synoviocytes, which play a role in joint destruction and pannus formation as rheumatoid arthritis (RA) progresses." (PMID 40542914, 2025). "Synovial fibroblasts with a high expression of FAPα have been identified as key effector cells in the inflammatory disease of rheumatoid arthritis." (PMID 38136590, 2023). "FAP was shown to be expressed in solid tumours, rheumatoid arthritis tissues, atherosclerotic plaques, and fibrotic tissues." (PMID 35562743, 2022). "This fits with the concept that FAP is expressed in areas of active tissue remodeling, similarly to how inflammation can trigger FAP expression in synovial fibroblasts in rheumatoid arthritis." (PMID 34884484, 2021). "FAP enzyme activity is known to be increased in certain liver diseases and decreased in certain malignancies, but remains unchanged in rheumatoid arthritis or scleroderma." (PMID 32315321, 2020). "To estimate the effect of re-directed FAP-specific T cells in chronically inflamed tissue, we used activated fibroblasts from patients with rheumatoid arthritis out of the effusion from inflamed joints." (PMID 23937772, 2013). "We investigated the expression of FAP by fibroblast-like synoviocytes (FLSs) and compared the synovial expression pattern in rheumatoid arthritis (RA) and osteoarthritis (OA) patients." (PMID 17105646, 2006). "Co-culture strongly increased the expression of activation markers such as FAP, PDPN, HLA type 2, and IL-6—markers of a myofibroblast phenotype associated with chronic inflammation, as seen in conditions such as rheumatoid arthritis, and indicative of immune crosstalk." (PMID 41321638, 2025). "List of clinical applications of targeted FAP imaging in rheumatoid arthritis." (PMID 40607439, 2025). "Fibroblast-like synoviocytes (FLSs) in rheumatoid arthritis (RA) synovial sites abundantly and stably overexpress FAP and play important roles in regulating the cellular immune, inflammatory, invasion, migration, proliferation, and angiogenesis responses in the synovial region." (PMID 37006278, 2023). "FAP expression has been observed in synovial tissue samples of rheumatoid arthritis." (PMID 36531015, 2022). "The nature of FAP expression does not only relate to tumor cell growth and migration, but also to chronic inflammation, such as rheumatoid arthritis, heart infarction and fibroses as well as wound healing, making it rather unspecific in a mixed disease setting and at early diagnosis." (PMID 34854061, 2022). "To overcome such potentially harmful effects of systemic FAP-positive cell depletion, we have recently developed and applied targeted photodynamic therapy (tPDT) to locoregionally eliminate FAP-positive cells in rheumatoid arthritis synovium." (PMID 34884484, 2021). "Likewise, FAP immunoreactivity is much higher in fibroblast-like synoviocytes of rheumatoid arthritis patients compared to osteoarthritis controls." (PMID 26300881, 2015). "Since these pathways have also been associated with FAP+IL11+ FB in the LP and with FAP+ FB that accumulate in rheumatoid arthritis and tumor microenvironments, we hypothesize that such changes in TRC are, at least in part, a general response of FB to chronic inflammation." (PMID 41379085, 2026).
rheumatoid arthritis (continued). "Thus, PDPN+FAPα+THY1+ cells play the role of an immune effector in the development of rheumatoid arthritis, capable of maintaining inflammation through the secretion of a different repertoire of chemokines and cytokines, as PDPN+FAPα+THY1− cells are capable of regulating osteoclast behavior." (PMID 38136590, 2023). "Recently, Ospelt and colleagues demonstrated that inhibition of the dipeptidylpeptidase activity of both FAP and DPP-4 (DPP-4-like activity) led to increased cartilage invasion by rheumatoid arthritis SF." (PMID 25600705, 2015). "A higher expression of FAP in the rheumatoid synovium as well as an increased expression by rheumatoid arthritis synovial fibroblasts (RASF) compared to OA led us to the hypothesis that increased FAP expression promotes matrix degradation in RA." (PMID 25600705, 2015).
hepatocellular carcinoma (22 papers, 2014 to 2025). A malignant tumor that arises from hepatocytes. "The AC007099.1/miR-7152/FAP pathway was found to be associated with immune infiltrations in patients with hepatocellular carcinoma." (PMID 35186170, 2022). "AC007099.1/miR-7152/FAP was found to be associated with immune infiltration in patients with hepatocellular carcinoma." (PMID 35186170, 2022). "Neuropeptide-associated fibroblast activation protein (FAP) may be an important risk factor for neurovascular metastasis in hepatocellular carcinoma." (PMID 35186170, 2022). "FAP was specifically expressed in the liver, and its low expression levels in hepatocellular carcinoma may be implicated in the poor prognosis of the disease." (PMID 35186170, 2022). "Therefore, the potential AC007099.1/miR-7152/FAP pathway was also found to be associated with immune infiltration in patients with hepatocellular carcinoma." (PMID 35186170, 2022). "In addition, upregulation of FAP under hypoxia has been shown to cause epithelial-mesenchymal transition, which enhance stemness, invasiveness and metastasis of cancers, and poor prognosis in hepatocellular carcinoma." (PMID 38017374, 2023). "We speculate that FAP may be an important risk factor for neurovascular metastasis of hepatoma." (PMID 35186170, 2022). "Notable investigational agents include the following: RAYZ-8009 (DOTA-RYZ-GPC3), targeting glypican-3 in hepatocellular carcinoma, and 177Lu-FAP-2286, directed against fibroblast activation protein (FAP) in stromal-rich tumours." (PMID 40725089, 2025). "In hepatocellular carcinoma, FAP+ fibroblast contributed to the formation of desert microenvironment around EMT‐HCC subtypes." (PMID 40292733, 2025). "AC007099.1 and FAP were highly expressed while miR-7152 expression was decreased in hepatocellular carcinoma." (PMID 35186170, 2022). "AC007099.1 and FAP were highly expressed, while miR-7152 expression was reduced in hepatocellular carcinoma." (PMID 35186170, 2022). "Furthermore, using in vivo tumor models established by xenografting HepG2-hFAP, U87, and primary hepatic carcinoma cell lines into mice, we validated the antitumor efficacy of FAP/IL-15 CAR-T therapy." (PMID 41455698, 2025). "The present study revealed that the expression of AC007099.1, miR-7152, and FAP in hepatocellular carcinoma could be used as a novel independent prognostic marker based on their observed roles during poor prognosis." (PMID 35186170, 2022). "For instance, bioinformatics analysis revealed that lncRNA AC009099 was positively correlated with FAP expression and may be regulated from the AC009099/miR-7152/FAP pathway in hepatocellular carcinoma, while lncRNA HIPK1-AS has shown similar effects in cervical cancer." (PMID 37006278, 2023). "For example, TREM2+ macrophages have been shown to suppress CD8+ T-cell infiltration in hepatocellular carcinoma, and SPP1+ macrophages interact with FAP+ fibroblasts to remodel the extracellular matrix." (PMID 39702278, 2024). "In fact, prior studies using FAP-inhibitor positron emission tomography (PET) radiotracers have shown higher 68Ga-FAPI vs. 18F-FDG uptake in CCA compared to hepatocellular carcinoma (HCC)." (PMID 39664608, 2024). "FAP expression was also evaluated in 138 Hepatocellular Carcinoma (HCC) samples via IHC." (PMID 37316886, 2023). "External validation confirmed positive correlations for FAP and angiogenesis receptors FLT1, KDR, and KIT as well as HIF1A and ETS1 in hepatocellular carcinoma but also in metastatic prostate cancer (Dream Team cohort)." (PMID 36672341, 2023). "Survival analysis then showed that the level of FAP expression significantly affected the overall survival (OS), progress free interval (PFI), and disease specific survival (DSS) of patients with hepatocellular carcinoma." (PMID 35186170, 2022). "The survival analysis results showed that FAP gene expression levels significantly affected the OS, PFS, and DSS in patients with hepatocellular carcinoma." (PMID 35186170, 2022).
hepatocellular carcinoma (continued). "Results of the survival analysis showed that the expression levels of the FAP gene had a significant effect on the OS, PFS, and DSS of hepatocellular carcinoma patients." (PMID 35186170, 2022). "Based on their expression levels, potential targets for hepatocellular carcinoma treatment may include AC00709, FAP, and miR-7152." (PMID 35186170, 2022).
non-small cell lung carcinoma (22 papers, 2016 to 2026). A group of at least three distinct histological types of lung cancer, including non-small cell squamous cell carcinoma, adenocarcinoma, and large cell carcinoma. "High FAP expression is associated with poor survival, high recurrence rates and more advanced stage in several cancers, including oral squamous cell carcinoma, ovarian cancer, pancreatic ductal adenocarcinoma and non-small cell lung cancer (NSCLC)." (PMID 35359378, 2022). "Non-small cell lung cancer (NSCLC): Paradoxically, higher stromal FAP levels have been linked to improved prognosis, reinforcing the need for tumor-specific interpretation in clinical settings." (PMID 41441395, 2025). "FAP was found to predict the efficacy of PD-1 blockade therapy in advanced non-small cell lung cancer." (PMID 40244052, 2025). "Patients with high FAP expression had a significantly shorter progression-free survival in immunotherapy of non-small cell lung cancer (NSCLC)." (PMID 38459511, 2024). "In non-small cell lung cancer and pancreatic adenocarcinoma, FAP overexpression suppressed lymphocyte-dependent immune reactions and reduced survival rate." (PMID 37316886, 2023). "The importance of evaluating effects of FAP-RLT in an immunocompetent setting is further emphasized by recent findings of FAP as a potential predictive biomarker for PD-1 blockade in non-small cell lung cancer patients, which highlights the immunosuppressive role of FAP or FAP + cells." (PMID 39008063, 2024). "Also, FAP overexpression affects survival by suppressing lymphocyte-dependent immune reactions in non-small cell lung cancer and pancreatic adenocarcinoma." (PMID 37316886, 2023). "However, in another study in non-small cell lung cancer (NSCLC), high density of FAP+CAFs was found to be associated with improved prognosis in patients with high expression of CD8 and CD3 T lymphocytes." (PMID 35222418, 2022). "In advanced non-small cell lung cancer (NSCLC), FAP is related to a reduced density of CD8+ T cells and immunosuppressive TME status." (PMID 37143134, 2023). "Additionally, Talabostat, a FAP enzyme inhibitor, also showed no significant therapeutic effect in clinical trials involving patients with non-small cell lung cancer." (PMID 40855046, 2025).
Cirrhosis (20 papers, 2006 to 2026). A chronic disorder of the liver in which liver tissue becomes scarred and is partially replaced by regenerative nodules and fibrotic tissue resulting in loss of liver function. "Moreover, FAP is a cell-associated dipeptidyl peptidase and gelatinase with dual specificity, expressed by activated hepatic stellate cells involved in tissue remodeling during cirrhosis." (PMID 41594225, 2026). "Prior to the onset of transformation of fibrosis into cirrhosis (F1–F4, weeks 3–7), FAP+ and SMA+ cells were localized in different places on histological specimens." (PMID 38434195, 2023). "The liver expression of FAP in cirrhosis was shown to correlate with the severity of fibrosis but was not exclusively expressed by α-SMA+ myofibroblasts, suggesting that FAP marks a differentially activated fibroblast state." (PMID 34439762, 2021). "Accordingly, FAP expression was significantly higher in CAFs from HCCs than in benign fibrous stroma from chronic hepatitis/cirrhosis specimens (P = 0.012)." (PMID 25126747, 2014). "In contrast, FAP expression was rarely found in benign fibrotic tissue of chronic hepatitis/cirrhosis." (PMID 25126747, 2014). "In this study, CCN2, epithelial membrane antigen (EMA), fibroblast activation protein (FAP), and keratin 19 (K19) expression was studied in 314 HCCs (cohort 1), 42 scirrhous HCCs (cohort 2), and 36 chronic hepatitis/cirrhosis specimens by immunohistochemistry." (PMID 25126747, 2014). "In comparison of tumor fibrous stroma of HCC and benign fibrous stroma of the liver, the expressions of CCN2, EMA, and FAP were investigated in specimens of chronic hepatitis/cirrhosis (n = 36)." (PMID 25126747, 2014). "Furthermore, FAP expression is activated in hepatic stellate cells during cirrhosis and correlates with fibrosis severity." (PMID 41594225, 2026). "Increased FAP expression in activated hepatic stellate cells and in plasma of patients with cirrhosis were reported, thus indicating that FAP could negatively regulate the hepatoprotective activity of FGF2126." (PMID 33277568, 2020). "We showed that FAP is a highly promising biomarker, as both tissue and circulating levels are low in healthy individuals, but FAP is elevated in diseased organs and cFAP is elevated in cirrhosis." (PMID 28582421, 2017). "Indeed, we observed a good correlation between FAP activity and FAP protein levels in human serum samples from both healthy individuals and patients with cirrhosis." (PMID 28970566, 2017). "Consistent with its role in fibrosis, FAP has been found to be expressed in fibroblasts and hepatic stellate cells (HSCs) activated in cirrhosis but not in normal human livers." (PMID 36531015, 2022). "FAPα is also expressed by stellate cells at the tissue remodelling interface in human cirrhosis but not in normal livers." (PMID 16507127, 2006). "Additionally, FAP was not expressed in the stromal cells of most cases of chronic hepatitis/cirrhosis, and it was only focally detected in stromal cells from three cases (3/36, 8.3%) of chronic hepatitis/cirrhosis." (PMID 25126747, 2014).
Cachexia (19 papers, 2016 to 2025). Severe weight loss, wasting of muscle, loss of appetite, and general debility related to a chronic disease. "Depletion of FAP+ stromal cells causes cachexia, leading to a loss of muscle mass despite adequate food intake." (PMID 38706713, 2023). "Depletion of FAPα-positive cells in healthy mice caused a cachexia-like syndrome, characterized by rapid weight loss and reduced muscle mass despite adequate food intake." (PMID 31058816, 2019). "Nevertheless, the applicability of these approaches might be limited because of the widespread expression of FAP, especially in bone marrow and muscle, and systemic targeting of FAP+ cells might result in cachexia, bone toxicity, muscle loss, or even death." (PMID 36708970, 2023). "Thus, loss of FAPα-positive fibroblasts from skeletal muscle was proposed to play a causal role in the muscle-wasting aspect of cachexia." (PMID 31058816, 2019). "These poor clinical results are potentially explained by recent studies that showed that stromal depletion in murine PDAC models can lead to reduced survival and that depletion of FAP-positive cells results in cachexia and anemia due to loss of bone marrow–derived stem cells." (PMID 28922779, 2018). "Using transgenic mice, it was shown that the systemic removal from the organism of cells expressing the FAPα gene led to the development of muscular dystrophy and cachexia." (PMID 38136590, 2023). "Ablation of FAP expressing cells resulted in cachexia and a reduction of erythropoiesis, suggesting that FAP+ cells in healthy tissues contribute to essential physiological functions." (PMID 35479076, 2022). "A study revealed that the depletion of FAP+ stromal cells leads to the cachexia and anemia." (PMID 40248695, 2025). "Although a study in mice demonstrated that depletion of FAPα+ cells can result in cachexia and anemia and FAPα+ cells were found to reside in most tissues, including muscle and bone marrow, studies investigating the potential use of FAPα as a therapeutic target in diseases are ongoing." (PMID 38783357, 2024). "Moreover, a T cell therapy against FAP-expressing cells in an animal model induced cachexia and lethal bone toxicity by unintentional targeting of FAP-expressing bone marrow stromal cells." (PMID 26893143, 2016). "Elimination of FAP‐expressing activated fibroblasts by treatment with chimeric antigen receptor T cells has been shown to reduce fibrosis and improve cardiac function in mice, but depletion of stromal cells expressing FAP from bone marrow could induce cachexia and anemia." (PMID 40384987, 2025). "For instance, due to the killing of multipotent bone marrow cells that express low levels of FAP, FAP CAR-T cells induced significant cachexia and lethal bone toxicities in mouse strains bearing a variety of subcutaneous tumors." (PMID 37784082, 2023). "Other trials using FAP-targeted CAR T-cells, reported less efficacy as well as fatal cachexia and bone toxicity as a result of off-target toxic effects triggered by the abolition of FAP + progenitor stromal cells." (PMID 37004047, 2023). "However, one previous study revealed that FAP-targeted CAR-T cells induced lethal ototoxicity and cachexia by killing pluripotent stem cells in the bone marrow stroma, which aroused great concern." (PMID 37046312, 2023). "However, third-generation FAP-targeting CAR-T cells in this study showed limited antitumor activity and induction of cachexia and other toxicities, which were attributed to the expression of FAP on bone marrow stromal cells that could also be recognized in an on-target/off-tumor fashion." (PMID 36284896, 2021).